RN7SL648P (RNA, 7SL, cytoplasmic 648, pseudogene)
Gene: Miscellaneous RNA gene on chromosome X (74,242,608 to 74,242,908, reverse strand). Ensembl gene ENSG00000265727.
Homologues: Orthologues: chimpanzee Metazoa_SRP (99% identical), macaque Metazoa_SRP (90% identical). Paralogues in human: RN7SL2 (82% identical), RN7SL1 (82% identical), RN7SL3 (80% identical), RN7SL7P (79% identical), RN7SL709P (78% identical), RN7SL543P (78% identical), RN7SL788P (78% identical), RN7SL296P (78% identical), RN7SL444P (78% identical), RN7SL45P (78% identical), RN7SL88P (78% identical), RN7SL220P (77% identical), and 705 more.